APOL2 (apolipoprotein L2)
Description:
May affect the movement of lipids in the cytoplasm or allow the binding of lipids to organelles.
Synonyms: ApoL-II
Tractability: Antibody: its Gene Ontology location is reachable by antibodies, with medium confidence. PROTAC: ubiquitination databases record sites on it; its protein half-life has been measured.
Gene: Protein-coding gene on chromosome 22 (36,226,209 to 36,239,954, reverse strand). Ensembl gene ENSG00000128335.
Subcellular location: Cytoplasm
Gene Ontology:
Molecular function: protein binding; high-density lipoprotein particle binding; lipid binding; signaling receptor binding
Biological process: acute-phase response; cholesterol metabolic process; lipid metabolic process; lipid transport; maternal process involved in female pregnancy; lipoprotein metabolic process
Cellular component: membrane; endoplasmic reticulum membrane; cytoplasm; extracellular region
Genetic constraint (gnomAD): Loss-of-function variants: 8 observed, 8.08 expected, observed/expected ratio (o/e) 0.99, 90% interval 0.58 to 1.7. That is too few expected variants to judge how well the gene tolerates losing a copy. Missense variants: 471 observed, 437.26 expected, observed/expected ratio (o/e) 1.08, 90% interval 1 to 1.16. Synonymous variants: 177 observed, 168.23 expected, observed/expected ratio (o/e) 1.05, 90% interval 0.93 to 1.19.
Homologues: Orthologues: chimpanzee APOL2 (98% identical), macaque APOL2 (75% identical), rat LOC120093819 (43% identical), rat Apol3l1 (42% identical), mouse Apol9b (37% identical), mouse Apol9a (36% identical), mouse Apol11a (34% identical), rat Apol9a (34% identical), mouse Apol10b (33% identical), mouse Apol11b (31% identical), mouse Apol10a (28% identical), zebrafish apol (22% identical), and 2 more. Paralogues in human: APOL1 (62% identical), APOL3 (52% identical), APOL4 (40% identical), APOL6 (29% identical), APOL5 (29% identical), APOLD1 (14% identical).
Diseases named in the same sentence as APOL2 in open-access papers:
APOL2 is named in the same sentence as 29 diseases in open-access papers, as found by Europe PMC text mining. Sharing a sentence is not in itself a finding about the gene and the disease. The quoted sentences say what the papers report.
schizophrenia (3 papers, 2017 to 2024). A major psychotic disorder characterized by abnormalities in the perception or expression of reality. "Prior works have found the gene APOL2 was upregulated in the brains of schizophrenic patients, and polymorphisms in this gene were linked to schizophrenia risk." (PMID 37055858, 2023). "ApoL2 gene variants are associated with schizophrenia and substance abuse." (PMID 39456672, 2024). "In 2008, a GWAS study on schizophrenia, a typical psychiatric disease, has confirmed that APOL2 may also contribute to the pathogenesis of schizophrenia given its potential contribution to psychiatric diseases." (PMID 29258237, 2017).
viral infection (3 papers, 2021 to 2025). "APOL2, mainly localized at the endoplasmic reticulum, is implicated in cholesterol biosynthesis and trafficking and is thought to mediate cell death induced by interferon-gamma or viral infection, indicating a role in inflammatory processes." (PMID 37055858, 2023).
bladder cancer (2 papers, 2019 to 2021). "GSDMB, CLEC2D, APOL2, TNFRSF14, and GBP2 were selected as prognostic genes in bladder cancer patients." (PMID 34708131, 2021).
acute lymphoblastic leukemia (1 paper, 2017). Leukemia with an acute onset, characterized by the presence of lymphoblasts in the bone marrow and the peripheral blood. "For ten of these reQTL genes the eQTL was absent under baseline condition (pbaseline > 0.01), including reQTL genes such as APOL2 potentially associated with glomerulosclerosis, PTGER4 with allergy, and PIP4K2A with acute lymphoblastic leukemia." (PMID 28814792, 2017).
autism (1 paper, 2020). Persistent deficits in social interaction and communication and interaction as well as a markedly restricted repertoire of activity and interest as well as repetitive patterns of behavior. "We only found this situation for some genes showing intra-population copy number variability in humans, such as PPP2R5C for autism or APOL2 for chronic kidney disease." (PMID 32392208, 2020).
cervical cancer (1 paper, 2015). A primary or metastatic malignant neoplasm involving the cervix. "In addition, a recent genomic study demonstrated that apolipoprotein L2 (APOL2) is markedly upregulated in cervical cancer." (PMID 25695263, 2015).
Cirrhosis (1 paper, 2023). A chronic disorder of the liver in which liver tissue becomes scarred and is partially replaced by regenerative nodules and fibrotic tissue resulting in loss of liver function. "Nomograms were constructed using sex, cirrhosis, BCLC stage, APOL2, APOL3 and APOL6 expression for RFS." (PMID 38017264, 2023). "Small tumor size; female sex; lack of cirrhosis; BCLC stage 0; high expression of APOL2, APOL3 and APOL6; and low AFP levels indicated higher survival rate in the GSE14520 cohort." (PMID 38017264, 2023).
colon cancer (1 paper, 2023). "Moreover, we transfected RKO colon cancer cells with APOL1-KO, APOL2-KO, APOL3-KO, APOL4-KO and APOL6-KO." (PMID 36923931, 2023).
diabetes (1 paper, 2024). "We observed a significantly higher protein expression of APOL1 by 12.8-fold in islets from three donors with (pre-)diabetes, while APOL2 and APOL6 were not significantly altered in these donors." (PMID 37924378, 2024).
hepatitis C virus infection (1 paper, 2021). A viral infection caused by the hepatitis C virus. "APOL2 was shown to inhibit Hepatitis C virus infection and APOL6 has been shown to inhibit poliovirus." (PMID 34252458, 2021).
liver fibrosis (1 paper, 2025). "Apolipoprotein L2 (APOL2) was recently reported to promote liver fibrosis upon transforming growth factor-β1 (TGF-β) stimulation of human hepatic stellate cells." (PMID 40503184, 2025).
malaria (1 paper, 2024). Malaria is a serious and sometimes fatal disease caused by a parasite that commonly infects a certain type of mosquito which feeds on humans. "Notably, complement genes (C1QA, C1QB, C1QC), apoptotic genes (PDL1, PDL2, APOL1, APOL2, FAS), inflammatory caspases (CASP1, CASP5), TLR pathway genes (TLR1, TLR4, TLR5, TLR8), cytokines (IL6, IL10), and granzyme (GZMB) were among the genes upregulated during symptomatic malaria." (PMID 39161730, 2024).
Nephropathy (1 paper, 2025). A nonspecific term referring to disease or damage of the kidneys. "Moreover, I provide evidence that the site of DP interaction with APOL2 precisely coincides with an APOL1 cholesterol-binding motif involved in kidney podocyte cytotoxicity causing APOL1 variant nephropathy, linking APOL-induced pathologies of these 2 diseases." (PMID 40503184, 2025). "Moreover, since IFN-I–induced APOL1 variant nephropathy is linked to both podocyte ER stress and fibrosis, it is possible that in the kidney, the APOL1 variants G1 and G2 mimic APOL2 activity in the liver." (PMID 40503184, 2025).
psoriasis (1 paper, 2025). An autoimmune condition characterized by red, well-delineated plaques with silvery scales that are usually on the extensor surfaces and scalp. "We identified 34 housekeeping genes associated with psoriasis and observed that the co-expression relationships between six genes (APOL2, DCUN1D3, UBE2F, HIGD1A, PPIF, and STAT3) and known psoriasis-related genes differed significantly between diseased and healthy individuals." (PMID 40959079, 2025).
triple-negative breast carcinoma (1 paper, 2021). An invasive breast carcinoma which is negative for expression of estrogen receptor (ER), progesterone receptor (PR), and human epidermal growth factor receptor 2 (HER2). "Recently, a 3’ untranslated region profile including APOL2 was reported to predict the LNM status in operative triple-negative breast cancer." (PMID 34368222, 2021).
tumor (5 papers, 2003 to 2025). "In this study, APOL2 expression in GC was found to be positively correlated with tumor progression, suggesting a potential association with poor prognosis." (PMID 40953331, 2025). "Kaplan‐Meier (KM) curve analysis revealed that increased APOL2 expression was associated with reduced overall survival (OS), which led us to further explore the association between APOL2 expression and tumor growth." (PMID 40953331, 2025). "Conversely, APOL2 exhibited markedly higher expression levels in tumor tissues compared with normal tissues." (PMID 40953331, 2025). "Ki67 staining revealed that the proliferation rate of tumor cells in the APOL2‐OE group was significantly greater than that in the control group, while γH2AX expression level was lower in the APOL2‐OE group than that in the control group upon IR treatment." (PMID 40953331, 2025). "IHC and Western blot assays confirmed these findings, revealing elevated APOL2 levels in tumor tissues." (PMID 40953331, 2025). "To validate these findings, we collected 108 clinical samples from GC patients to evaluate the levels of APOL2 protein in tumor tissues and their corresponding adjacent normal tissues via immunohistochemical staining." (PMID 40953331, 2025). "Collectively, our findings demonstrate that FN disrupts the APOL2‐Ku80 interaction, leading to Ku80 destabilization and decreased its expression, thereby abolishing APOL2‐mediated radioresistance and restoring tumor cell sensitivity to IR." (PMID 40953331, 2025). "To further verify these observations, we performed Western blot analyses on five paired samples of tumor and adjacent normal tissues, which confirmed that APOL2 expression was significantly higher in tumor tissues compared to adjacent normal tissues." (PMID 40953331, 2025). "We found that CD8+ T cells and M2 macrophages were closely related to TNFRSF14 and APOL2, and the expression of TNFRSF14 and risk score were strongly associated with tumor purity, immune score, various inflammatory factors, and others." (PMID 34708131, 2021). "We established a subcutaneous tumor xenograft model by using WT cells and APOL2‐KO cells." (PMID 40953331, 2025). "Tumor growth was fastest in the vector group without any intervention, while tumor growth was significantly inhibited in the APOL2‐KO plus IR group." (PMID 40953331, 2025). "Interestingly, most CIDGS-related genes, such as XRCC6, ST13, PES1, EFHD2, APOL2, ACTR2, and CDCP1, were markedly upregulated in HNSCC tumor samples, whereas several other genes, such as MARCO, MRC1, and CD83, were upregulated in healthy samples." (PMID 38666027, 2024).
cancer (4 papers, 2019 to 2025). A tumor composed of atypical neoplastic, often pleomorphic cells that invade other tissues. "The association between APOL2 and cancers was not widely explored." (PMID 34368222, 2021).
infection (3 papers, 2018 to 2025). The state of being infected such as from the introduction of a foreign agent such as serum, vaccine, antigenic substance or organism. "Among these transcripts we identified the apolipoprotein L gene family including, APOL1, APOL2 and APOL6 with up to a fivefold increase of expression (q value ≤ 0.05) after infection with ZIKV." (PMID 39885287, 2025).
APOL2 also shares sentences with these, for which no sentence is quoted: Allergy (1 paper); atherosclerosis (1); chronic kidney disease (1); diabetic cardiomyopathy (1); gastric cancer (1); glomerulosclerosis (1); Obesity (1); papillary thyroid carcinomas (1); prostate carcinoma (1); psychiatric diseases (1); substance abuse (1).